IL10 (interleukin 10)
Diseases named in the same sentence as IL10 in open-access papers (continued):
Sharing a sentence is not in itself a finding about the gene and the disease.
leishmaniasis (continued). "There are few studies published on IL-10 polymorphisms and leishmaniasis, and most of them did not report any standardization on control groups." (PMID 35778471, 2022). "In leishmaniasis, the induction of a Th2 response, with increased IL-4, IL-5 and/or IL-13 production, and regulatory responses, via the production of IL-10 and/or transforming growth factor β (TGF-β), modulate the protective immune response and favor Leishmania persistence." (PMID 33777015, 2021). "For Leishmania amazonensis, one of the main etiological agents of leishmaniasis in the Amazonian region, a Th2 response against infection is generally developed, confirmed by the presence of high levels of IL-4 and IL-10, and accompanied by the production of IgG1 antibody isotypes." (PMID 34253188, 2021). "IL-10 is mainly generated by Treg cells, Th2 cells, and M2 macrophages during leishmaniasis." (PMID 34140933, 2021). "Dogs that develop the symptomatic form of leishmaniasis may exhibit higher IL-10 and lower IFN-γ concentrations in the blood, while the inverse it true in asymptomatic dogs." (PMID 33465107, 2021). "IL12 and IL10 are two of the major cytokines which control the fate of Leishmaniasis." (PMID 35126456, 2021). "IL-10 expressionsuppresses the Th-1 cellular response to leishmaniasis." (PMID 32347041, 2021). "These authors also observed an in vivo exacerbation of leishmaniasis lesions, and they associated with IL-10 induction, but not IL-4, to this immune response downregulation." (PMID 34276650, 2021). "This inhibitory role of IL-10 is exemplified during leishmaniasis." (PMID 33415318, 2020). "Interestingly, an increasing trend in IL-10 production was noted in the cell culture supernatants of dogs with leishmaniasis, especially under SLA stimulation." (PMID 31961868, 2020). "Hence, increased IFN-γ and IL-6 levels as well as decreased amount of IL-10 and IL-4 skewed to the healing process in leishmaniasis." (PMID 30811391, 2019). "IL-10 is the most important regulatory cytokine in leishmaniasis." (PMID 31119102, 2019). "IL-10 is the major regulatory cytokine in human leishmaniasis." (PMID 31119102, 2019). "IL-10 shows anti-inflammatory effects, and its role in leishmaniasis remains controversial." (PMID 30627118, 2018). "So far, the cellular sources of IL-10 remain unidentified in leishmaniasis." (PMID 29915577, 2018). "Thus, it is possible that IL-10—when secreted by salivary nucleoside-generated iTregs—contributes to the exacerbation of leishmaniasis." (PMID 25849562, 2015). "However, IL10 is involved in mediating parasite persistence, regulating Th2 cell expansion and controlling cell-mediated lesion development in leishmaniasis." (PMID 25569338, 2015). "In addition, we analyzed the mechanism underlying this enhanced protection and demonstrated that the suppression of the early antigen-dependent IL-10 secretion seems to contribute to the protection mediated by DC-based vaccination against leishmaniasis." (PMID 23825956, 2013). "Since T cells and professional APC are important cellular sources of IL-10, we compared leishmaniasis disease progression in T cell-specific, macrophage/neutrophil-specific and complete IL-10-deficient C57BL/6 as well as T cell-specific and complete IL-10-deficient BALB/c mice." (PMID 23825956, 2013). "Thus, taken together, our studies with cells from leishmaniasis patients indicate that similar to the murine model, both IL-10 and IFN-γ inhibit IL-17 production." (PMID 23555256, 2013). "Furthermore, a dendritic cell-based vaccination against leishmaniasis efficiently suppresses the early secretion of IL-10, thus contributing to the control of parasite spread." (PMID 23825956, 2013). "Similarly, the production of IL-17 by cells from leishmaniasis patients was also regulated by IL-10 and IFN-γ." (PMID 23555256, 2013).
leishmaniasis (continued). "Thus, IL-10 has previously been shown to be important in regulating the immune response to leishmaniasis, but a murine model that mimics the severe pathology seen when an exaggerated Th1 type immune response develops in leishmaniasis remains unexplored." (PMID 23555256, 2013). "A balance between the proinflammatory response characterized by the production of IFN-γ and TNF, and the regulatory response with the production of IL-10 has been observed in individuals exposed to the Leishmania braziliensis in endemic areas of leishmaniasis in Brazil." (PMID 23209879, 2012). "Since IL-10 is a strong suppressor of host cytokine production and promotes disease progression in leishmaniasis, it is possible that the cytokine-suppressive effects we observed could be attributable to Leishmania-augmented IL-10 production." (PMID 20205812, 2010). "In addition to the canonical type 1 and type 2 T helper cell responses, IL-10, a cytokine originally described as a type 2 cytokine, plays an important role in leishmaniasis." (PMID 19292771, 2009). "Lack of IFN-γ activity may be related to the simultaneous presence of elevated levels of IL-10, as IL-10 seems to be the main macrophage deactivating cytokine in human leishmaniasis." (PMID 16364177, 2005). "Besides M2 macrophages, lymphocyte subpopulations are significant IL‐10 sources in leishmaniasis." (PMID 40947759, 2025). "In addition, it was observed that there was an increase in the number of CD4+ T cells producing IL-10, which is also positive, since a regulatory profile is also important during leishmaniasis, as an uncontrolled Th1 response is also part of the pathogenesis of this disease." (PMID 40006676, 2025). "Unlike the phenomenon of resistance, susceptibility to leishmaniasis is concomitantly characterized by the amplification of interleukin-10 (IL-10) levels, a cytokine molecule recognized for its anti-inflammatory activity and ability to exert inhibitory effects on the Th1-type immune response." (PMID 39065160, 2024). "Although other meta-analyses have shown the association between IL-10 polymorphisms and other diseases, the present meta-analysis of five case–control studies did not indicate IL-10 SNPs as a risk factor or protective factor for the progression of leishmaniasis." (PMID 35778471, 2022). "As yet, there is no information to suggest that IL-4 and IL-10 are engaged in downregulating the Th1-type immune response in human leishmaniasis caused by L. donovani; however, further study is needed to identify the role of Th2 cells in L. martiniquensis infection in both human and murine models." (PMID 34977224, 2021). "IL-10 is associated with chronicity of the lesion in C57BL/6 mice and in L. major infected IL-10 knock out group of C57BL/6 mice, sterile cure occurs with no protection against challenge, so present of IL-10 is necessary for induction of protection in leishmaniasis." (PMID 32685122, 2020). "We, however, did not examine the IL-6 level and concentrated on IL-10 but can hypothesize that IL-6 promotes the anti- inflammatory effect of IL-10 in leishmaniasis.The level of IFN-γ remained high, until the patients converted into symptomatic VL, and showed significantly low production." (PMID 32555598, 2020). "However, few data is available on the effect of IL-10 neutralization in human leishmaniasis." (PMID 26495321, 2015). "However, when expressed in large quantities, IL-10 may have deleterious effects during leishmaniasis, leading to an early suppression of innate and acquired immune responses, pathogen proliferation, and aggravation of the disease." (PMID 26538837, 2015). "IL-10 may act in the control of cell-mediated lesion development in leishmaniasis." (PMID 25309922, 2014). "Thus, this study demonstrates that the IL-17 pathway might be an important therapeutic target for the treatment of severe leishmaniasis in patients where the IL-10 regulatory function is compromised." (PMID 23555256, 2013).
leishmaniasis (continued). "However, the association of IFNγ+IL-10+ CD4+ T cells with disease progression in leishmaniasis has suggested that through IL-10 production, these cells may contribute to parasite persistence and/or disease pathology." (PMID 22911108, 2012). "Serum levels of the cytokines IL-10, IL-6, IL-12, and IFN-γ were increased in dogs with leishmaniasis." (PMID 41623056, 2026). "Leishmaniasis is an immunosuppressive disease, where CD4 secreting IFN-γ cells have been shown to be required for parasite control, and IL-10 levels are related to parasite persistence." (PMID 40737310, 2025). "Similarly in human leishmaniasis, TREG cells were characterized in skin lesions of patients with CL, PKDL, and MCL caused by different New World and Old World Leishmania species, suggesting a regulatory role of these cells through IL-10 production that contributes to the parasite persistence." (PMID 38469319, 2024). "Given the significance of maintaining a balance between inflammatory and regulatory cytokines for the development of protective immunity against leishmaniasis, we calculated the IFN-γ/IL-10 and GrB/IL-10 ratios for individuals in our cohort." (PMID 38064516, 2023). "The pathogenesis of leishmaniasis and host defense primarily depends on two critical cytokines: IFN-γ and IL-10." (PMID 38274802, 2023). "A set of cytokines and chemokines can influence the cellular immunity to leishmaniasis, comprising, but not limited to, IFN-γ, IL-4, IL-12, IL-13, TNF-α, and IL-10." (PMID 34140933, 2021). "In experimental models of leishmaniasis, strong CD40-CD40L signaling induced IL-12 production by macrophages whereas weak signaling induced IL-10 production." (PMID 30619775, 2018). "It has been shown that high ratio of IFN-γ to IL-10 provided the best correlate of protective immunity and it has been suggested that a correct balance of pro-inflammatory to regulatory cytokines may be involved in the outcome of human leishmaniasis and in the prediction of vaccine success." (PMID 28416006, 2017). "Similar to other infections, IL-10 and TGF-β have been identified as important cytokines in leishmaniasis that are involved in homeostatic mechanisms and the control of tissue damage caused by excessive inflammation." (PMID 25706930, 2015). "It clearly shows that an efficient vaccine against leishmaniasis should not only induce IFN-γ-, TNF- and IL-2-secreting memory T cells, but also needs to prevent the development of antigen-specific IL-10-secreting T cells." (PMID 23825956, 2013). "IL-10-producing DCs have been described in chronic EVL and CD4+ T cells which produce IL-10 (including natural Tregs, Tr-1 and CD4+ Th1 cells) have all been described in various forms of leishmaniasis in mouse and man." (PMID 24363630, 2013). "Of note, vaccination simulation with LeishChim induced production of IFNγ in higher levels compared to IL-10, suggesting that vaccination with LeishChim could induce the TH1-type immune response that is protective against leishmaniasis." (PMID 36851182, 2023). "Several studies have shown the importance of IL-10 and TGF-β in different types of leishmaniasis." (PMID 32849363, 2020). "It was believed that classical Treg cells probably produce IL-10 but studies have ruled out this in human leishmaniasis." (PMID 29915577, 2018). "The production of IFN-γ, TNF-α, granzyme B, IL-5 and IL-10 by SLA-stimulated PBMCs, and of IFN-γ, TNF-α and IL-2 by SLA-stimulated whole blood, could be used to indicate exposure to leishmaniasis, especially for patients subjected to induced immunosuppression." (PMID 26496365, 2015). "In a non-healing mouse model of Leishmaniasis, high frequency of IL-10 producing regulatory T cells (CD4+CD25+FoxP3+) is observed at local site." (PMID 25032977, 2014). "Taken together, these results indicate that IL-17 can mediate extensive pathology in leishmaniasis if not regulated by IL-10, and that in the absence of IL-10, IFN-γ plays a critical role in regulating IL-17 production." (PMID 23555256, 2013).
leishmaniasis (continued). "Using a mouse model of leishmaniasis, we investigated what cytokines contribute to increased pathology when IL-10-mediated regulation is absent." (PMID 23555256, 2013). "In leishmaniasis, macrophages, CD4+ T regulatory cells and CD4+ Th1 cells produce IL-10, although the relative importance of each of these sources is debated and may change as the infection progresses." (PMID 23555256, 2013). "In leishmaniasis, the absence of IL-10 can lead to significantly better clearance of the parasites in both cutaneous and visceral leishmaniasis." (PMID 23555256, 2013). "Finally, we show that IL-10 and IFN-γ regulate the IL-17 responses of cells from human patients with leishmaniasis." (PMID 23555256, 2013). "The co-production of IL-10 by IFNγ-producing CD4+ T cells is not novel for leishmaniasis, however, and is now a recognized feature of Th1 cell differentiation." (PMID 22911108, 2012). "Lack of IFN-γ activity may be related to the simultaneous presence of elevated levels of IL-10 and TGF-β, the macrophage deactivating cytokines in human leishmaniasis." (PMID 20668544, 2010). "Besides IL-10, TGF-β has potent immunosuppressive properties, enhances disease progression and may prevent cure and protective immunity development against leishmaniasis." (PMID 32295617, 2020). "Unlike leishmaniasis recidivans, IL-10 is thought to play a major role in the etiology of PKDL." (PMID 28629171, 2017). "Likewise, the lack of IFN-γ may result in relatively higher levels of IL-10 in human leishmaniasis resulting in MΦ deactivation and parasite proliferation." (PMID 31024534, 2019). "Here, we used a murine model of leishmaniasis to identify the factors involved in this pathology, and found that mice infected with Leishmania major developed severe lesions in the absence of IL-10 or IL-10 signaling, and similar to patients, contained high levels of IFN-γ and IL-17." (PMID 23555256, 2013). "However, the significantly higher frequency of IL-10 responders in non-infected individuals could be a consequence of the constant exposure of the study population to chronic infectious diseases, such as schistosomiasis and leishmaniasis." (PMID 33777015, 2021). "Notably, we also performed flow cytometry analyses in two individuals (B3 and B8) living in non endemic area of leishmaniasis and who did not exhibit neither PBMC proliferation nor IL-10 production after stimulation with SGE." (PMID 21991402, 2011).
Anxiety (113 papers, 2006 to 2026). Intense feelings of nervousness, tension, or panic often arise in response to interpersonal stresses. "Our results suggest the existence of immune–personality signatures in healthy older dogs, specifically involving serum TNF-α and IL-10 levels in association with fear- and anxiety-related traits." (PMID 40867746, 2025). "Anxiety has also been associated with lower levels of anti-inflammatory cytokines such as IL-4 and IL-10." (PMID 41462928, 2025). "Reduced levels of IL-10 have been described in patients with symptoms of anxiety, depression, and suicidal risk in a population study." (PMID 40507852, 2025). "A 21-day supplementation with L. helveticus R0052 prevented the increased anxiety-like behavior induced by a Western-style diet in both the wild-type mice and the interleukin-10 deficient (IL-10−/−) 129/SvEv mice with immune system dysregulation." (PMID 37966492, 2024). "A splenic increase in Il1β and Tlr4 with cortical Vcam expression strongly associated with the anxiety-like behavior while splenic IL-10 associated with IL-1β from both the PFC and cortex, predicted depressive-like behavior." (PMID 34248950, 2021). "Taken together, these results suggest reduced activity and heightened anxiety levels due to the interaction of IL-10 deficiency and AIA." (PMID 37220589, 2016). "In IL-10 knockout mice, symptoms of depressive behaviour and reduced motivation have been observed, while enhanced IL-10 signalling in the amygdala has been associated with decreased anxiety and the regulation of GABAergic neurotransmission." (PMID 41008291, 2025). "Low IL-10 has been linked to anxiety, depressive symptoms, poor sleep, and somatic morbidity." (PMID 41150816, 2025). "However, at this moment, we don’t know the exact mechanism by which lowered levels of IL-10 are linked to higher anxiety severity in GAD patients." (PMID 38902708, 2024). "Among people with alcohol use disorder, IL-10 was negatively associated with anxiety score." (PMID 35815053, 2022). "Additionally, the anxiety of spouse/partner relationships was significantly associated with IL-6/IL-10 ratios." (PMID 34360332, 2021). "Results demonstrated that women receiving the M-O-M-STM intervention had longitudinally sustained lower TNF-α/IL-10 ratios than the control group, and it was significantly associated with psychosocial measures of anxiety, specifically for fears of labor and spouse/partner relationships." (PMID 34360332, 2021). "Pioglitazone demonstrated efficacy in improving both core (social withdrawal and repetitive behaviors) and associated (irritability, hyperactivity, and anxiety) autism symptoms and did significantly decrease the pro-inflammatory cytokine IL-6 and increase the anti-inflammatory cytokine IL-10." (PMID 30498564, 2018). "Finally, we found that IL-10 dependent increases in anxiety are associated with the up-regulation of specific HPA axis signatures." (PMID 37220589, 2016). "In our study, the positive association of anti-inflammatory, neuroprotective, and emotional regulatory IL-10 with anxiety and activity, along with the inverse association between IL-1β and anxiety, may represent this regulatory balance and buffered inflammatory load in these aging cats." (PMID 41268300, 2025). "Second, in the HA rats, liver damage and anxiety were associated with an imbalance between GCs and cytokines that expressed in the decrease of blood Cort with a simultaneous increase of IL-1 and IL-2 and with a decrease of IL-4 and IL-10 concentrations in the blood and in the liver." (PMID 37629192, 2023). "The cats with lower IL-1β had increased odds of exhibiting more severe anxiety, as assessed by the FCDRC, whereas IL-10 emerged as a positive predictor of greater severity of changes in both the anxiety and activity domains." (PMID 41268300, 2025).